IL6 (interleukin 6)
Diseases named in the same sentence as IL6 in open-access papers (continued):
Sharing a sentence is not in itself a finding about the gene and the disease.
Cognitive impairment (continued). "There is a greater likelihood of cognitive impairment in individuals with consistently high or increasing levels IL-6; each doubling of IL-6 changes over 20 yrs." (PMID 36778590, 2022). "Those with cognitive impairment had more proinflammatory diets (2.2 (0.3) vs. 1.1 (0.1), p = 0.001), and significantly higher IL-6 concentrations (4.1 (0.8) vs. 2.5 (0.2), p = 0.004) than women with normal cognitive function." (PMID 34371834, 2021). "Our findings establish dysregulated IL-6 signaling as a key mechanism linking memory/cognitive impairment and metabolic dysregulation in AD." (PMID 33911072, 2021). "In turn, cognitive impairment seems to correlate with peripheral levels of IL-1β, IL-4, IL-6 and IL-12, and considering only the AChR population, also with peripheral levels of TNF-α." (PMID 34501305, 2021). "It has been previously shown that WBC increased NO levels while lowering IL-6 levels in the blood among patients with mild cognitive impairments (MCI), which was indicative of anti-inflammatory effects." (PMID 34356664, 2021). "In this study, we investigate the mutual interactions between cancer stem cells and the tumor cells that facilitate cognitive impairment during long term TZB therapy by developing a mathematical model that involves IL-6 and the key apoptotic regulation." (PMID 34669701, 2021). "Collectively, these results point to IL-6 as a link between cognitive impairment and peripheral metabolic alterations in AD." (PMID 33911072, 2021). "It has been observed that in patients with MDD, increased levels of IL-6 correlated with attention deficit disorder, and one study showed that its increase was prior to the incidence of cognitive impairment in patients with MDD." (PMID 34575258, 2021). "They further see that microglia can take up tau, leading to Il-6 production, overall bringing new insights into the mechanism of sevoflurane-mediated cognitive impairment." (PMID 33980987, 2021). "TNF-α and IL-1β in the ischemic brain can reportedly induce the production of IL-6, and increased IL-6 levels in the serum and cerebrospinal fluid are related to cognitive impairment." (PMID 34457113, 2021). "The role of inflammatory cytokines, especially TNF-α, IL-1β, IL-6, and IL-8, is well-established in neurodegeneration and cognitive deficits." (PMID 34103066, 2021). "Elevated serum levels of proinflammatory cytokines, including interleukin 6 (IL-6), tumor necrosis factor-alpha (TNF-α), and C-reactive protein, can cause cognitive impairment." (PMID 33627087, 2021). "In our study we also determined that postmenopausal women with diagnosed cognitive impairment had higher levels of IL-6 and were less educated and less physically active." (PMID 34371834, 2021). "Not only does IL-6 reduce serotonin concentrations, but synaptic neuroplasticity is also impaired by interleukin-1β (IL-1β), which is released in vivo, contributing to cognitive impairment." (PMID 34299040, 2021). "Pro-inflammatory factor IL-6 is considered to be an independent predictor of postoperative cognitive impairment, and perioperative inflammatory factors are closely related to the occurrence of postoperative cognitive impairment in elderly patients." (PMID 34248475, 2021). "Elevated levels of IL-6 correlate with the extent of cognitive deficit and psychosis in 22q11.2 deletion syndrome." (PMID 35046931, 2021). "Despite some controversy in the literature, previous meta-analyses have concluded that IL-6 is increased in both cerebrospinal fluid (CSF) and plasma of mild cognitive impairment (MCI) and AD patients compared to control individuals." (PMID 33911072, 2021). "NF-κB-induced IL-6 expression in astrocytes was shown to indirectly mediate HIV-associated complement 3 expression to promote neuroinflammation and cognitive impairment." (PMID 33171974, 2020). "For instance, higher peripheral IL‐6 levels correlated with greater cognitive deficits in some studies." (PMID 32790155, 2020).
Cognitive impairment (continued). "Correlations were found between IL-6, IL-8, and IL-10 levels and some clinical parameters, especially the severity of cognitive impairment." (PMID 33362607, 2020). "Surgery is associated with an increase in peripheral IL-6 and HMGB1 and with cognitive impairment 6 weeks postoperatively." (PMID 33187477, 2020). "According to Qi and collaborators, the NKT treatment reduced the levels of TNF-α, IL-1β, and IL-6 in models of cognitive impairment and dementia in rats, corroborating the data from our pleurisy model." (PMID 32392744, 2020). "In fact, HAND patients show elevated IL-6 levels in cerebrospinal fluid, which are associated with HIV compartmentalization and cognitive impairment." (PMID 33171974, 2020). "Previous experiments showed that the LPS-treatment cognitive impairment mice model enhanced the secretion of IL-1β, IL-6, and TNF-α and the expression of iNOS and COX-2 with increased NO production." (PMID 32796824, 2020). "Our results suggest that AC significantly inhibited the cognitive deficits caused by SPS via increased expression of pro-inflammatory cytokines, including tumor necrosis factor-α and interleukin-6, in the rat brain." (PMID 30621666, 2019). "Here, we showed that tibial fracture surgery induced cognitive deficit and production of proinflammatory cytokines interleukin-6 (IL-6) and IL-1β, along with microglia and astrocyte activation, neuronal damage, and blood-brain barrier (BBB) disruption." (PMID 31011286, 2019). "In the present study, inhibiting mast cell degranulation by the mast cell stabilizer cromolyn limited microglia activation and release of TNF-α and IL-6, and alleviated LPS-induced cognitive impairment." (PMID 31130850, 2019). "In summary, our results propose that release of cytokines such as IL-1β, IL-6 and TNF-α and also MDA as lipid peroxidation index in brain tissue following TBI cause cognitive impairment and LTP insufficiencies." (PMID 30524680, 2018). "Our findings demonstrated that associations between mid‐life baseline IL‐6 and CRP with later life cognitive impairment were explained by educational attainment and modifiable life course factors." (PMID 31328177, 2018). "Greater severity of cognitive impairment measured using the ACE-R and the MMSE was associated with having a significantly lower level of IL-1beta, IL-2 and IL-4, and a higher level of IL-6 and TNF-alpha." (PMID 29248892, 2018). "To understand the underlying mechanism how COX2 contributes cognitive deficits in the CUMS-treated rats, we assayed the levels of inflammatory biomarkers, including TNF-α, prostaglandins E2 (PGE2) and IL-6." (PMID 28415673, 2017). "We give an overview of IL-6 role in the onset and progression of this disorder, also considering cognitive impairment and metabolic changes in patients with schizophrenia." (PMID 29163240, 2017). "Concurrent with cognitive impairment, our study showed that LPS-exposed mice had significantly higher level of hippocampal inflammatory cytokine (IL-6)." (PMID 29137271, 2017). "Our previous studies have shown that surgery under local anesthesia induces an age-dependent cognitive impairment in mice, and anesthetic isoflurane and sevoflurane can increase IL-6 level." (PMID 28848542, 2017). "Increasing SIRT3 and decreasing CypD can attenuate cognitive impairment and neuroapoptosis, and protect the integrity of mitochondrial membrane from damage and restore the protein expressions of IL-6, TNF-α, and caspase-3." (PMID 28236057, 2017). "Physical exercise improves TBI-induced cognitive deficits by ample release of IL-6, synapsin I, and other nerve growth factors." (PMID 28438174, 2017). "Here we extend from those studies with our focus on patients with recent onset of illness who nevertheless have both predicted cognitive deficits and elevated levels of IL-6 in plasma and CSF." (PMID 27070405, 2016). "Higher plasma IL-6 concentrations were strongly related to severity of self-perceived cognitive impairment (p = 0.001)." (PMID 27701469, 2016).
Cognitive impairment (continued). "For instance, data collected from a 20-years cohort study demonstrate greater possibility of cognitive impairment in individuals with increased IL-6." (PMID 27054030, 2016). "Present findings further contribute to the growing evidence that supports the role of the pro-inflammatory cytokine IL-6 in the occurrence of cognitive impairment post-chemotherapy." (PMID 27701469, 2016). "Specially, increased levels of serum IL-6 and IL-18 correlated with cognitive impairment in patients with cirrhosis of the liver and minimal hepatic encephalopathy." (PMID 26420028, 2015). "Patients with mild cognitive impairment (MCI), a condition associated with increased risk of dementia, show improvement of cognitive function as well as reduced peripheral IL-6 and tumour necrosis factor α (TNF-α) levels after repetitive physical exercise." (PMID 26434635, 2015). "In patients with minimal HE, cognitive impairment correlates with serum levels of inflammatory cytokines IL-6 and IL-18." (PMID 26420028, 2015). "These IL-6 increase and cognitive impairment were blocked by ketorolac, an anti-inflammatory reagent." (PMID 23915963, 2013). "Similar to our study, a more recent study showed that exposure of 6-day old mice to 3% sevoflurane for 2 h each day for 3 days increased IL-6 in the brain tissues and resulted in cognitive impairment of these mice when they were more than one month old." (PMID 23915963, 2013). "A recent study showed IL-6 knockout mice were refractory to LPS-induced increases of cytokines in the brain and cognitive deficits eluding to the potential permissive effects of IL-6 during LPS-induced sickness." (PMID 21595956, 2011). "Recent work has explored the relationship of inflammation and cognitive function indicating an inverse association of levels of interleukin-6 and CRP with incident cognitive impairment, with mixed results regarding rate of change in cognitive function." (PMID 19638207, 2009). "Thus, inflammatory cytokines IL-6, IL-1β, IL-13, and TNFα are elevated at this longer phase and are related to cognitive deficits and/or post-acute sequelae." (PMID 41516418, 2026). "For instance, in aging, an inflammatory state is present, and this could lead to the disruption of the blood–brain barrier and promote cognitive impairment through the peripheral inflammatory cytokines such as IL-6 that participate in the regulation of BBB." (PMID 40004217, 2025). "To identify biomarkers specific to HF and cognitive impairment, we showed that serum biomarkers for neurodegenerative disease, NfL, and cytokines, IL-6, IL-12p40, IL-15, MIP-1α, TNFα, and TNFβ, levels were significantly higher in HF participants compared to healthy control participants." (PMID 41200931, 2025). "Persistent immune activation, cytokine release (e.g., IL-6, TNF-α), and microglial activation have been linked to neuroinflammation, which may contribute to fatigue, headaches, and cognitive impairment." (PMID 40217997, 2025). "Elevated levels of peripheral IL-6 may also be related to general cognitive deficits in individuals with schizophrenia and MDD." (PMID 39911538, 2025). "Additionally, they influence the concentrations of pro-inflammatory cytokines such as tumor necrosis factor-α (TNF-α) and interleukin-6 (IL-6), which contribute to alleviating primary symptoms, including cognitive impairments." (PMID 40612741, 2025). "The measurement of circulating IL-6 could be used as a screening test to identify AIS patients with cognitive impairment." (PMID 40305179, 2025). "In this regard, pro-inflammatory agents such as IL-6 appear to be a key driver of cognitive decline, whereas the anti-inflammatory cytokine IL-10 may play a protective role against alcohol-induced cognitive impairments." (PMID 41268373, 2025).
Cognitive impairment (continued). "Additionally, vitamin D supplementation ameliorated cognitive impairment and altered neurodegenerative (Aβ1-40, Aβ1-42, p-Tau, and Neprilysin) and inflammatory markers (IL-6, IL-1β, TNF-α, and NF-κβ) in the scopolamine-induced rat model." (PMID 41473190, 2025). "Our study aligns with prior research, demonstrating that aerobic exercise suppresses the activation of M1 phenotype microglia in the hippocampus of mice with AS-induced cognitive impairment and reduces the expression of inflammatory cytokines IL-6, TNF-α, and IL-1β." (PMID 40556958, 2025). "In SCZ patients, IL-1β levels were associated with increased severity of positive symptoms and overall psychopathology on the PANSS, as well as with cognitive deficits (attention, working memory, sustained attention, and social cognition) and impaired executive functions, similarly to IL-6." (PMID 41007867, 2025). "T. gondii infection induces the synthesis and upregulation of proinflammatory cytokines such as interleukin (IL)-6, IL-8 and tumor necrosis factor alpha (TNF-α), biomarkers of chronic inflammation associated with aging, neurodegenerative disorders and cognitive impairment." (PMID 41018675, 2025). "When exploring differences in blood biomarkers between PCC groups stratified according to cognitive impairment, higher levels of interleukin 6 and lower levels of D-dimer were found in cognitively altered PCC participants, compared with non-cognitively altered PCC." (PMID 40008326, 2025). "IL-6 level was increased in mild cognitive impairment condition." (PMID 40843259, 2025). "Furthermore, the main cytokines, including interleukin-1β, tumor necrosis factor-α, and interleukin-6, and the activation of microglia and astrocytes lead to the disruption of the blood–brain barrier and to cognitive impairment." (PMID 41470817, 2025). "A recent systematic review with metanalyses found that IL6 is among the most studied cytokines, with higher IL6 concentrations in AD patients compared to controls and in mild cognitive impairment (MCI) subjects compared to controls, and similar findings for TNFR-1 levels." (PMID 39825168, 2025). "The cognitive deficit could also be aggravated by high brain exposure to pro-inflammatory cytokines, including IL-1β, IL-6, and TNF-α." (PMID 39777720, 2025). "Although previous studies reported increased IL-6 CSF levels in NMOSD patients and some associations with more severe clinical and cognitive deficits, we did not observe differences in IL-6 levels between NMOSD AQP4 + patients, RRMS patients, and NIC." (PMID 41057549, 2025). "Alisol A was shown to lead to neurovascular protection in cerebral ischemic mice through the activation of the AKT/GSK3β signaling pathway; the compound attenuated the neurological deficits and cognitive deficits and inhibited IL-6 and IL-1β expression, in addition to promoting neuronal survival." (PMID 40070574, 2025). "BMMs depletion reduced hippocampal IL-6 elevation and alleviated cognitive deficits." (PMID 40914484, 2025). "Similarly, captopril decreased the deleterious impact of TNF on the BBB integrity in addition to repressing IL-6 levels following lipopolysaccharide intoxication in an experimental model of learning and cognitive deficits in rats." (PMID 39809925, 2025). "Similarly, chronic sleep restriction in mice increases neuroinflammation via pro-inflammatory cytokines (e.g., TNF-α, IL-6), contributing to cognitive deficits." (PMID 40958991, 2025). "IL-6 signaling disorders caused by mutations in the ligand-binding subunit of IL6R (IL6R gene) may also be the cause of psychiatric and cognitive disorders." (PMID 38646100, 2024). "It has been shown that neuronal apoptosis and microglia activation in hyperuricemia-mediated cognitive deficits mice are ameliorated by blocking the Myd88/NF-ĸB pathway to modulate the expression of the inflammatory factors IL-6 and the caspase family in mice serum." (PMID 38257230, 2024).
Cognitive impairment (continued). "However, excessive production or elevated levels of IL-6 can lead to neuroinflammatory reactions and neurodegeneration (which are known to be related to cognitive impairment)." (PMID 38892402, 2024). "Raised IL-6 and TNFα levels appear central to PASC/long COVID and complications, such as the increased risk of cardiovascular events, persist long after the acute infection, as does the neuroinflammation and associated cognitive deficits (“brain fog”)." (PMID 39000027, 2024). "Our findings revealed that OI treatment significantly alleviated anesthesia/surgery-induced cognitive impairment, concomitant with reduced levels of the neuroinflammatory cytokines IL-1β and IL-6, as well as suppressed activation of microglia and astrocytes in the hippocampus." (PMID 38649932, 2024). "Therefore, one of the pathways of FH supplementation to prevent cognitive impairment was the reduction of IL-6 gene expression." (PMID 39446794, 2024). "Sevoflurane induced tau phosphorylation at Ser202 and Thr205 residues in neurons, and tau was transmitted from neurons to microglia via extracellular vesicles (EV) or non-EV pathways, activating the NF-kB signaling pathway and leading to IL-6 generation and cognitive impairment." (PMID 36937655, 2023). "For example, a study conducted over a 20-year period involving approximately 2,000 patients has provided evidence indicating a higher cognitive impairment probability in individuals exhibiting recurrent elevations or progressive increases in interleukin (IL)-6 levels." (PMID 38089627, 2023). "Although the specific mechanisms for cognitive impairment remain unknown, it is of particular interest that levels and expression of IL-6 are increased in the impaired subgroup, both centrally and peripherally." (PMID 37091543, 2023). "Furthermore, they reduced cognitive impairment-like behavior, IL-6 expression, FOXO3a activation, and NF-κB-positive cell population in the hippocampus, GA, and colon, while hippocampal brain-derived neurotropic factor expression increased." (PMID 37872562, 2023). "Furthermore, increased IL-6 levels after surgery were found to lead to postoperative cognitive impairment through IL-6 trans-signaling in mouse CA1 neurons." (PMID 37735415, 2023). "A previous meta-analysis showed higher peripheral levels of soluble tumor necrosis factor receptor 2, monocyte chemoattractant protein-1, and IL-6, along with decreased IL-8 levels, in patients diagnosed with mild cognitive impairment when compared with controls." (PMID 38089627, 2023). "It is generally acknowledged that neuroinflammation plays an important role in the pathogenesis of Alzheimer’s disease and there are more inflammatory markers (TNFα, IL-1β, IL-6, IL-10) in patients with AD and mild cognitive impairment (MCI) than in healthy controls." (PMID 37081917, 2023). "Similarly, excessive level of Escherichia coli in the gut microbiota stimulates microgliosis and activates TNF-α, IL-12, and IL-6, eventually resulting in cognitive impairments." (PMID 37237920, 2023). "RUNX1 belongs to master regulators for the age-dependent microglia module and increases the level of G9a through histone lysine methylation, leading to the increase of neuroinflammatory markers such as interleukin-6, tumor necrosis factor-α and then cognitive impairment in rats." (PMID 37187578, 2023). "Blood studies showed that higher levels of pro-inflammatory markers were linked with a more severe motor phenotype (IFN-γ, TNF-α, IL-2, and IL-10), faster motor progression (CRP and IL-6), cognitive impairment (IFN-γ, TNF-α, IL-2, and IL-10), and worse sleep quality (CRP)." (PMID 36337703, 2022). "High concentrations of inflammatory markers such as interleukin-6 levels may correlate with poor gait speed performance and more severe cognitive impairment." (PMID 36438013, 2022). "We next examined whether manipulation of peripheral IL-6 affected injury-related microglial reactivation and cognitive impairment." (PMID 36160165, 2022).